TRIM63 (tripartite motif containing 63)
Diseases named in the same sentence as TRIM63 in open-access papers (continued):
Sharing a sentence is not in itself a finding about the gene and the disease.
gastric cancer (1 paper, 2025). A primary or metastatic malignant neoplasm involving the stomach. "ZKSCAN1 is significantly involved in lymph node metastasis and vascular invasion in gastric cancer, while there are no relevant reports on TRIM63." (PMID 40490947, 2025).
Hypoxemia (1 paper, 2022). An abnormally low level of blood oxygen. "Hypoxemia-induced muscle wasting was shown to increase MuRF1/Trim63 and atrogin-1/Fbxo32 expression possibly mediating muscle wasting." (PMID 35615361, 2022).
Immunodeficiency (1 paper, 2021). Failure of the immune system to protect the body adequately from infection, due to the absence or insufficiency of some component process or substance. "Interestingly, premature aging and muscle tissue expression disorders were often detected in immunodeficiency mice, and MYH7 and TRIM63 gene expression disorders were also detected." (PMID 33436826, 2021).
PEComas (1 paper, 2024). "We also identified high levels of TRIM63 RNA-ISH staining in three of five (60%) PEComas, a subset of which are known to harbor TFE3 fusions." (PMID 38393424, 2024).
postmenopausal osteoporosis (1 paper, 2019). Metabolic disorder associated with fractures of the femoral neck, vertebrae, and distal forearm. "Gene expression profiles suggested that SMAD4, CACNG1, and TRIM63 may have vital roles in the molecular mechanism of postmenopausal osteoporosis and that miR-331 may be a potential biomarker for postmenopausal osteoporosis, however, further studies are required." (PMID 31064048, 2019).
renal cell carcinoma (1 paper, 2024). "Given the discovery of RNA in situ hybridization (RNA-ISH) for TRIM63 as a sensitive and specific marker of MiTF-family aberration renal cell carcinomas, we sought to evaluate its utility in the workup of ASPS." (PMID 38393424, 2024).
restrictive cardiomyopathy (1 paper, 2025). A type of heart disorder referring to the inability of the ventricles to fill with blood because the myocardium (heart muscle) stiffens and looses its flexibility. "Notably, one study reported a TRIM63 missense variant (C145Y) in patients with restrictive cardiomyopathy (RCM), a condition that shares pathophysiological features, particularly diastolic dysfunction, with HCM." (PMID 40332812, 2025).
rhabdomyoma (1 paper, 2024). A benign mesenchymal tumor arising from skeletal or cardiac muscle. "In addition, one case of rhabdomyoma included in the current study demonstrated significant TRIM63 expression (H-score 280)." (PMID 38393424, 2024). "TRIM63 RNA-ISH staining in a single case diagnosed as rhabdomyoma may reflect overexpression of constitutive gene transcripts, as TRIM63 is expressed in normal skeletal muscle; indeed, in cases with nontumoral/adjacent benign skeletal muscle, low-level TRIM63 RNA-ISH staining was observed." (PMID 38393424, 2024).
Skin Cutaneous Melanoma (1 paper, 2025). "We analyzed TCGA database and observed that TRIM63, a E3 ligase, was significant higher in Skin Cutaneous Melanoma (SKCM), compared to that in normal skin tissues." (PMID 41315179, 2025).
cancer (103 papers, 2013 to 2026). A tumor composed of atypical neoplastic, often pleomorphic cells that invade other tissues. "While the function and regulatory mechanisms of TRIM63 have been extensively studied in skeletal muscle under different conditions, such as cancer, sepsis, diabetes, and renal failure, its involvement in tumors remains relatively understudied." (PMID 41315179, 2025). "Similar to Fos, Trim63 showed decreased expression in the exercised mice, while it showed increased expression in the cancer-bearing mice." (PMID 35801156, 2022). "Among the 52 deregulated genes identified in our analysis, six of the nine studies included in the meta-analysis have evaluated the expression of Trim63 and Fbxo32 as molecular markers of muscle atrophy in cancer cachexia." (PMID 31013615, 2019). "MuRF-1/Trim63 and Atrogin1/Fbxo32 are well-known E3 ligases that are upregulated in conditions that lead to muscle wasting, such as those seen in chemotherapy, cancer cachexia, glucocorticoid treatment, and muscle disuse." (PMID 38234397, 2023). "Trim63 protein localizes to the Z-line and M-line lattice of myofibrils and interacts with numerous signaling pathways, such as the microtubule-dependent signaling pathway in muscle or cancer regulating SUMO-related pathways." (PMID 35801156, 2022). "Six studies evaluated expression of both FBXO32 and TRIM63 in patients with cancer." (PMID 31498843, 2019). "In addition to the four genes (Fos, Col1a1, Trim63, and Six2), our study identified other potential molecular factors of high-intensity aerobic exercise, which may prevent cancer proliferation." (PMID 35801156, 2022). "Despite these limitations, our study clearly suggests that the high-intensity aerobic exercise resulted in changes in the expression of muscle-derived anticancer genes (Fos, Col1a1, Trim63, and Six2) that may account for the cancer-preventive effect of aerobic exercise." (PMID 35801156, 2022). "In particular, the expression of well characterized muscle-specific ubiquitin ligases, namely atrogin-1/MAFbx, MuRF1/TRIM63 and, more recently, MUSA 1 and SMART increases rapidly upon a variety of stressors, such as GC and pro-inflammatory cytokines, cancer cachexia and other pathological states." (PMID 34209043, 2021).
tumor (99 papers, 2009 to 2026). "IDH1 mutation in CT26 tumor-bearing mice resulted in increased expression of Ube2d1, Trim63, and Fbxo32, while ivosidenib treatment inhibited the upregulation of UPP-related enzymes." (PMID 37741882, 2023). "We observed a significant (p < 0.05, multiple t test with Holm-Sidak multiple testing correction) ~ 20-fold increase in Trim63 (a transcript encoding MuRF1, an E3 ubiquitin ligase associated with muscle atrophy), in tumor-bearing mouse muscle." (PMID 32151276, 2020). "Therefore, TRIM63 RNA-ISH staining would be expected in not only TFE3 fusion-associated neoplasms (like ASPS) but also in some non-TFE3-fused neoplasms." (PMID 38393424, 2024). "As expected, both the weight and volume of tumor growth were significantly decreased following Trim63 knock-down." (PMID 41315179, 2025). "Our study reveals that IRF-8 exerts a tumor suppressive role in neoplastic cells, wherein the reinstatement of IRF-8 through TRIM63 abrogation elicits diverse cellular processes leading to tumor cell eradication." (PMID 41315179, 2025). "And TRIM63 S69A knock-in resulted in a significant reduction in tumor weight, growth rate, and improved survival duration compared to the group with TRIM63 WT." (PMID 41315179, 2025). "Results showed that KPC tumor-induced increase in the mRNA levels of Fbxo32, Trim63, Map1lc3b, Cd36, Acox3, and spliced-Xbp1 (sXbp1) in skeletal muscle were significantly reduced by treatment of mice with 4μ8C." (PMID 40655023, 2025). "In summary, the findings from our data analysis suggest that the regulatory axis of TRIM63/IRF-8 plays a significant role in promoting tumor progression, both within tumor cells and the immune microenvironment." (PMID 41315179, 2025). "The A549 tumour-induced expression of skeletal muscle atrophy-related genes, such as Mstn, Fbxo32, and Trim63 was mitigated upon treatment with 2% Pc-Ex." (PMID 35406121, 2022). "On a molecular level, we observed significant decreases in Trim63, Fbxo32, and Perp in muscles of mice bearing T4 shPerp 145 and T4 shPerp 146 tumors compared with control T4 shScr tumor mice." (PMID 34874916, 2022). "The WFA 4 mg/kg group exhibited a significant reduction in relative gene expression of Fbxo30, Fbxo32, Trim63, and Traf6 compared to the tumor-free vehicle-treated group (p < 0.0001, p = 0.04, p = 0.02, p < 0.0001, respectively)." (PMID 33718372, 2021). "Interestingly, genes encoding ubiquitin ligases (Trim63, Fbxo32/MAFBx, Fbxo31, and Fbxo30/Musa1) that target muscle proteins and serve as markers of muscle atrophy were found to be transcriptionally upregulated in the gastrocnemius muscles from the tumor‐bearing mice." (PMID 32730698, 2020). "Treatment with Ab‐RAGE reduced tumour cell‐derived factors' ability to decrease myotube diameter, up‐regulate Trim63, and increase pho‐p38 MAPK levels." (PMID 32159297, 2020). "Lastly, antibodies against the muscle-specific proteins ITGB1BP3/MIBP and TRIM63 reacted consistently with ASPS tumor sections with cytosolic localization." (PMID 19146682, 2009). "Similarly, the mice bearing C8161 with TRIM63 S69E showed a significant increase in tumor weight, growth rate, and worse survival duration compared to the group with TRIM63 WT." (PMID 41315179, 2025). "Notably, the immunodepleting of CD8+ T cells eliminates the benefit of TRIM63-depletion on tumor growth." (PMID 41315179, 2025). "Moreover, TRIM63, an E3 ubiquitin ligase, ultimately associates with IRF-8 resulting in degradation of the tumor suppressor gene to promote tumor progression." (PMID 41315179, 2025). "Furthermore, the basal levels of TRIM63 were specifically highly expressed in SKCM across all the tumor types." (PMID 41315179, 2025). "Consistent with in vitro observations, Trim63 (young, P = 0.0187; aged, P = 0.045) and Fbxo32 (young, P = 0.0491; aged, P = 0.0262) gene expression was increased in skeletal muscle lysates prepared from tumor-bearing mice." (PMID 34874916, 2022).
tumor (continued). "To investigate whether inhibition of ERK activation prevents TRIM63 phosphorylation and IRF-8 degradation, we found that treatment of BRAF-mutant tumor cells with Dabrafenib and Vemurafenib suppressed TRIM63 phosphorylation at S69 while concurrently increasing IRF-8 protein levels." (PMID 41315179, 2025). "Although FOR did not recover body weight in the presence of DOX treatment or potentiate the tumor weight reduction, it was able to recover the grip strength and the muscle mass (p<0.05), in addition to reducing the gene expression of Trim63 (p < 0.01) and Fbxo32 (p < 0.05)." (PMID 38234397, 2023). "To investigate the role of TRIM63/IRF-8 axis, we primary attempted to check the effect of IRF-8 in tumor cells." (PMID 41315179, 2025). "TRIM63 m-RNA transcripts in the RNA-ISH were seen as strong, punctate brown dots in both the nucleus and cytoplasm of the tumor cells." (PMID 38393424, 2024). "To determine if aging affects molecular determinants of muscle wasting in our models, we measured the expression of the atrogenes Fbxo32, Trim63, Foxo3a, and Cathepsin-L in skeletal muscle of young and old LLC and C26 tumor cell injected mice." (PMID 35008253, 2021). "In the tumor-bearing animals, treatment with WFA led to a statistically significant dose-dependent transcriptional downregulation of Fbxo30, Fbxo32, Trim63, and Traf6 compared to the tumor-bearing vehicle-treated group (p < 0.0001 for all comparisons)." (PMID 33718372, 2021). "Furthermore, ivosidenib preserved skeletal muscle mass by decreasing the expression of the E3 ligases Trim63 and Fbxo32, as well as inhibiting the production of D2HG in tumor and serum." (PMID 37741882, 2023).
myopathy (18 papers, 2013 to 2024). A disease of the muscle in which the muscle fibers do not function properly. "Likewise, the combined germ line deletion of Trim63/MuRF1 and Trim54/MuRF3 as well as the deletion of Trim55/MuRF2 and Trim54/MuRF3 caused a myosin storage myopathy of the heart and skeletal muscle in mice." (PMID 34572540, 2021). "For example, MYL1, MYOM2, TRIM63 and PSMD4 have been broadly associated with myopathies but not directly to LVNC or DCM yet, and could therefore be considered as potential targets to investigate." (PMID 37644440, 2023).
bacterial infections (1 paper, 2023). "In addition, we found that the dynamics of TRIM63 expression during both bacterial infections in mice (in the lungs) was opposite to that in humans (in A549 cells), which means that the mouse model is not suitable for studying the role of TRIM63 in human bacterial-caused diseases." (PMID 37686095, 2023).
TRIM63 also shares sentences with these, for which no sentence is quoted: Obesity (16 papers); infection (10); Hyperglycemia (8); chronic obstructive pulmonary disease (7); muscular dystrophy (7); renal failure (6); type 2 diabetes (6); cardiac disease (5); endotoxemia (5); hyperlipidemia (4); osteoporosis (4); age (3); colon cancer (3); dysferlinopathy (3); leukemia (3); metabolic disorders (3); myocardial infarction (3); myocardial ischemia (3); pulmonary hypertension (3); viral infection (3); vitamin D deficiency (3); amyotrophic lateral sclerosis (2); Arthritis (2); Calpainopathy (2); Cerebral ischemia (2); Cirrhosis (2); inflammation (2); ischemia (2); lung fibrosis (2); renal carcinoma (2).
A further 78 diseases each share a sentence with TRIM63 in 2 papers or fewer.